ENSG00000285920 (novel protein)
Gene: Protein-coding gene on chromosome 15 (41,284,007 to 41,380,996, forward strand). Ensembl gene ENSG00000285920.
Genetic constraint (gnomAD): Loss-of-function variants: 18 observed, 25.52 expected, observed/expected ratio (o/e) 0.71, 90% interval 0.49 to 1.05. Missense variants: 305 observed, 333.25 expected, observed/expected ratio (o/e) 0.92, 90% interval 0.83 to 1.01. Synonymous variants: 136 observed, 124.82 expected, observed/expected ratio (o/e) 1.09, 90% interval 0.95 to 1.26.